CD40 (CD40 molecule)
Diseases named in the same sentence as CD40 in open-access papers (continued):
Sharing a sentence is not in itself a finding about the gene and the disease.
metastatic cancer (2 papers, 2020 to 2024). A carcinoma which has spread from the original site of growth to another anatomic site. "Such an implementation could be investigated with anti-CD40 as an immunoadjuvant, thereby extending the use of radiotherapy to treatment of both local and advanced/metastatic cancer, with curative intent leveraging the abscopal effect." (PMID 32331490, 2020).
mycobacterial infection (2 papers, 2021 to 2025). "It has been reported that CD40 knockout mice infected with M. avium show effects on IL-12 and IFN-γ, which indicates that CD40 makes an important impact on the development of immune response caused by mycobacterium infection." (PMID 35046920, 2021). "During mycobacterial infection, the IFN-γ-mediated upregulation of CD40 plays a crucial role in immunoregulation and also increases metalloproteinase activity." (PMID 41394879, 2025).
nasal polyp (2 papers, 2013 to 2025). "As was observed for S-100, the CD1a and CD40 double stained-positive cells were mostly in the submucosa of the nasal polyps." (PMID 23737902, 2013). "The present study demonstrates that DCs are involved in the pathogenesis of nasal polyps and the presence of CD40-positive DCs suggests that this was related to the reciprocal interaction between the DCs and T lymphocytes." (PMID 23737902, 2013). "In the present study, immunohistochemical and double immunostaining methods were used to detect the expression and distribution of S-100 and CD1a/CD40 in the nasal polyps, to gain information concerning the role of DCs in their pathogenesis." (PMID 23737902, 2013). "In addition, the CD40-positive nature of the surface of the DCs suggested that DCs may react in the nasal polyps through reciprocal interaction with T lymphocytes." (PMID 23737902, 2013).
non-alcoholic steatohepatitis (2 papers, 2021). "Our group has shown that mice with spherocytosis and chronic hemolysis were resistant to anti-CD40-induced necro-inflammatory liver disease and nonalcoholic steatohepatitis (NASH)." (PMID 34054870, 2021).
oral cancer (2 papers, 2021 to 2025). "Although OK-432 treatment upregulated the expression levels of the IL-12p40, p35, and CD40 genes, CM from oral cancer cells downregulate these genes." (PMID 34209347, 2021).
pancreatitis (2 papers, 2022 to 2025). Inflammation of the pancreas. "We focused on investigating the diagnostic utility of exo-CD40 and exo-CD25 as a novel marker for PDAC with plasma samples from patients with PDAC, pancreatitis, and clinical control individuals." (PMID 40003965, 2025). "As both diseases, namely pancreatitis and TRALI, are closely linked, we investigated the involvement of the CD40L/CD40 protein interaction in the regulation of pancreatitis immediately following the onset of TRALI." (PMID 35185916, 2022). "However, the markers that demonstrated a significant distinction between PDAC, pancreatitis, and clinical control groups were exo-CD40 and exo-CD25." (PMID 40003965, 2025). "In summary, these findings underscore the significance of exo-CD40 in distinguishing PDAC and pancreatitis patients from clinical control individuals." (PMID 40003965, 2025). "In order to ascertain the significance of exo-CD40 in distinguishing PDAC, pancreatitis patients and clinical control individuals, we evaluated it by performing plasma CD40 ELISA." (PMID 40003965, 2025). "The reduced CD40 signal on plasma exosomes from PDAC and pancreatitis patients compared to those from clinical controls could be due to lower levels of circulating dendritic cells (DCs) and a significant increase in the absolute number of B cells." (PMID 40003965, 2025). "Similar to exo-CD40, age did not influence the expression of exo-CD25 in clinical control, pancreatitis, and PDAC patients." (PMID 40003965, 2025). "Our research findings revealed that the level of exosomal CD40 expression is significantly lower in patients with PDAC and pancreatitis compared to non-cancer patients (p < 0.0001)." (PMID 40003965, 2025).
Pneumocystis carinii pneumonia (2 papers, 2018 to 2024). "Patients with mutations in CD40L or CD40 are particularly susceptible to Pneumocystis carinii pneumonia (PCP) and Cryptosporidium infection." (PMID 30131802, 2018). "Besides fungal infections, xenotransplantation with corresponding anti-CD40-based immunosuppression can be associated with the activation of latent herpes viruses, including HCMV, as well as external infections such as Pneumocystis pneumonia." (PMID 39200391, 2024).
soft tissue sarcoma (2 papers, 2008 to 2025). A malignant neoplasm arising from muscle tissue, adipose tissue, blood vessels, fibrous tissue, or other supportive tissues excluding the bones. "Notably, TEM1, VEGFR-1, EGFR, VEGFR-2, IGF-1R, PDGFRα, and CD40 are highly expressed in the tumor cells of soft tissue sarcoma." (PMID 40258773, 2025).
thromboembolic disease (2 papers, 2019 to 2020). "The administration of anti-CD154 neutralizing antibodies is effective in animal models but unfortunately causes thromboembolism, and various alternative strategies are sought for, such as the inhibition of CD40 signaling intermediates with peptides." (PMID 32089648, 2020).
thymoma (2 papers, 2017 to 2023). A neoplasm arising from the epithelial cells of the thymus. "CD40 and β5t expression were associated with the Masaoka-Koga stage of thymoma and TSCC." (PMID 36797681, 2023). "With histological classification moving from A to AB, B1, B2, B3, and TSCC, we found an inverse correlation between thymoma histological classification and CD40 and AIRE expression (Spermanr= -0.326, p = 0.024; Spermanr= -0.419, p < 0.001 respectively)." (PMID 36797681, 2023). "For AB thymoma, CD40 was more strongly expressed in tumor cells around the cysts." (PMID 36797681, 2023). "In B1 thymoma, CD40 was more expressed in the medullary islands than in the cortical areas." (PMID 36797681, 2023). "In this study, we aimed to explore the expression of thymic cortical epithelial markers (β5t, PRSS16, and cathepsin V) and medullary epithelial markers (claudin-4, CD40, and AIRE) in thymoma and TSCC and its correlation with histological classification, staging, and prognosis." (PMID 36797681, 2023).
thyroid cancer (2 papers, 2015 to 2022). "Using the TISIDB database, we demonstrated that ALDH1A1/A3/B1 had significant negative correlations with immune-stimulating genes, such as CD276, TMEM173, TNFSF9, CD70, TNFRSF25, and CD40 in thyroid cancer." (PMID 35280765, 2022). "CD40 stimulation inhibits cell growth and Fas-mediated apoptosis in a thyroid cancer cell line." (PMID 26679379, 2015).
vitiligo (2 papers, 2018 to 2019). Generalized well circumscribed patches of leukoderma that are generally distributed over symmetric body locations and is due to autoimmune destruction of melanocytes. "Mice that had been treated with combination SBRT anti-CD40 also developed vitiligo at the site of rechallenge." (PMID 30245691, 2018). "SBRT and anti-CD40 was so effective at augmenting T cell priming, that memory CD8 T cell responses to both tumor and self-antigens were induced, resulting in vitiligo in long-term survivors." (PMID 30245691, 2018).
acne (1 paper, 2021). An inflammatory process of the sebaceous glands which is characterized by comedones, nodules, papules and/or pustules on the skin. "The hypothesis of an immune response burden in uninvolved skin in patients with acne is reinforced by the fact that we observed a high percentage of activated mast cells and macrophages (according to CD86 and CD40 expression) in UI biopsies." (PMID 34650562, 2021).
acne inversa (1 paper, 2022). "Several more drugs with new immunological targets such as IL-12/23, IL-17, IL-23, IL-36, C5a, CD-20, CD-40, LTA4, and CXCR1/2 are presently under investigation for the treatment of acne inversa." (PMID 36077114, 2022).
acute GVHD (1 paper, 2018). "In contrast, in biopsies from inflamed skin taken during acute GVHD, the increase in HLA class II-expressing cells was not caused by macrophages, but by an increase in inflammatory DCs, because HLA class II-positive cells expressed CD11c, CD40, CD54, and CD86 in separate stainings." (PMID 29535719, 2018).
alcohol (1 paper, 2019). "Genetic knockout of CD40 (CD40-/-) or the caspase-activating TNF-related apoptosis-inducing ligand (TRAIL) receptor (TR-/-) protected mice from alcohol-induced injury." (PMID 32047496, 2019).
amyloid (1 paper, 2024). "Compared with controls, Aβ CAR-Ms upregulated CD86, MHC-II, CD40, and PD-L1 and downregulated CD206 after coincubation with amyloid-laden brain slices." (PMID 38516884, 2024).
arteriopathy (1 paper, 2017). "Studies have identified soluble CD40L as an important link between platelet activation and inflammation, and the blockade of the CD40 and CD40L system has been shown to suppress allograft transplant arteriopathy." (PMID 28975088, 2017).
Atherosclerotic lesion (1 paper, 2015). A lesion associated with atherosclerosis, a multifactorial and multipart progressive disease manifested by the focal development within the arterial wall of lesions, that ranges from the development of a fatty streak, plaque progression, and plaque disruption. "CD40 is upregulated in endothelial cells in the atheroma, ApoE-/- CD40-/- mice exhibit diminished atherosclerotic lesions and CD40-/- mice have decreased neointima formation after arterial injury." (PMID 26710229, 2015).
atopic dermatitis (1 paper, 2022). "Recently, researchers have identified a small subset of skin DCs called mregDCs with high expressions of BIRC3, LAMP3, IL15, CD40, and CCR7, and this subset has been thought to be associated with wound healing and the exacerbation of atopic dermatitis." (PMID 35280984, 2022).
B-cell neoplasm (1 paper, 2014). A group of heterogeneous lymphoid tumors generally expressing one or more B-cell antigens or representing malignant transformations of B-lymphocytes. "CD40 is expressed on multiple B-cell neoplasms including DLBCL and is a potential target for immunotherapy." (PMID 24919462, 2014).
Ba (1 paper, 2022). "Particularly, we previously published results showing that Ba infection induces DCs maturation, as evidenced by the up-regulation of CD86, CD80, CCR7, CD83, MHC-II, MHC-I and CD40 at 24 h post-infection." (PMID 36441810, 2022).
bacterial sepsis (1 paper, 2011). "Mice deficient in the expression of CD40 have been shown to have improved survival during bacterial sepsis as a result of decreased induction of IL-6, IL-10, IL-12 and IFNγ expression." (PMID 21949840, 2011).
benign prostatic hyperplasia (1 paper, 2024). A non-cancerous nodular enlargement of the prostate gland. "Recent studies show that macrophages have a role in immune inflammation and proliferation in benign prostatic hyperplasia through the androgen receptor and CD40/CD40L signaling pathway." (PMID 39703506, 2024).
bone metastasis (1 paper, 2019). Transfer of a neoplasm from its primary site to bones. "Moreover, CD40 protein expression in tumor infiltrating lymphocytes (TILs) and CAFs was positively associated with metastatic spread while BAFFR protein expression in CAFs was negatively associated with bone metastasis (p = 0.041)." (PMID 31137630, 2019).
brain inflammation (1 paper, 2010). "Indeed, the preclinical evaluation of a monoclonal antibody against CD40 has shown beneficial activities in an MS model when administered early in the disease development, as well as after the onset of brain inflammation." (PMID 20634952, 2010).
Cachexia (1 paper, 2018). Severe weight loss, wasting of muscle, loss of appetite, and general debility related to a chronic disease. "Macrophages were depleted in vivo using F4/80 antibody and mice monitored for response to IL-2/anti-CD40 immunotherapy, as well as weight loss (i.e., cachexia)." (PMID 30459812, 2018). "Cachexia is a comorbidity condition in elderly cancer patients and can impair the host’s ability to tolerate anti-cancer treatments, as seen in the present study by rapid weight loss with IL-2/anti-CD40 immunotherapy for the elderly mice." (PMID 30459812, 2018). "Furthermore, in elderly, but not young mice, macrophage inhibition prevented the IL-2/anti-CD40 immunotherapy treatment-induced cachexia." (PMID 30459812, 2018).
Candidemia (1 paper, 2025). A form of invasive candidiasis where species of CANDIDA are present in the blood. "The highest upregulated expressions in isolated candidemia included CXCL6, LAP-TGF beta-1, CXCL1, CXCL11, and CD5, while in candidemia with bacterial co-infection, CXCL11, CD40, uPA, CXCL1, CXCL10, and IL-18 were the most abundantly upregulated." (PMID 41229429, 2025). "The proteomic profile in candidemia included eight of the most significantly upregulated DEPs: CXCL11, LAP-TGF beta-1, CD40, CXCL1, CXCL6, IL18, CXCL10, and uPA." (PMID 41229429, 2025).
cervical dysplasia (1 paper, 2020). "We still observed significant correlation of two immune co-stimulatory molecules, CD40 and CD28, with the level of genital inflammation across patients with HPV infection, cervical dysplasia, and healthy controls." (PMID 32802959, 2020).
cervical squamous cell carcinoma (1 paper, 2023). A squamous cell carcinoma arising from the cervical epithelium. "Therefore, we aimed to investigate the correlation between single nucleotide polymorphisms (SNPs) of the CD40 gene and susceptibility to cervical squamous cell carcinoma (CSCC) in a population from the northeastern Han Chinese population." (PMID 37691121, 2023).
chordoma (1 paper, 2021). Chordomas are rare malignant tumors arising from embryonic remnants of the notochord in axial skeleton. "In particular, the knockdown of DEPDC1B resulted in not only a significant upregulation of Caspase3, sTNF-R1, but also downregulation of Bcl-2, CD40, HSP27, IGF-1sR, XIAP, Livin, Survivin in chordoma cells." (PMID 34330893, 2021).
CNS lymphoma (1 paper, 2023). "In addition, EVs bearing these molecules were significantly and positively associated with non-CNS lymphoma: PD-L1 (OR = 1.94; 95% CI: 1.01 – 3.72); CD40 (OR = 2.66; 95% CI: 1.12 – 6.35); TNF-RII (OR = 9.64; 95% CI: 2.52 – 36.86); IL-6Rα (OR = 8.34; 95% CI: 1.73 – 40.15)." (PMID 37809067, 2023).
delirium (1 paper, 2024). A disorder characterized by confusion; inattentiveness; disorientation; illusions; hallucinations; agitation; and in some instances autonomic nervous system overactivity. "The results of the annotation of the screened SNPs suggest that CD27 and CD40 may be key molecules mediating the involvement of B cells in delirium risk." (PMID 38379709, 2024).
dermatomyositis (1 paper, 2021). Dermatomyositis (DM) is a type of idiopathic inflammatory myopathy characterized by evocative skin lesions and symmetrical proximal muscle weakness. "For example, CD40 was intensely expressed in all subacute cutaneous lupus erythematosus (SCLE), discoid LE (DLE), and dermatomyositis (DM) lesions." (PMID 35095896, 2021).
diabetic foot ulcer (1 paper, 2022). "Real-Time Polymerase Chain Reaction: RT-PCR for the gene expression of CD68, CD86, CD206, CD40, IL-6, IL-1β, and TNF-α revealed increased relative gene expression (normalized to housekeeping gene 18S) in diabetic foot ulcer tissues compared to control tissues." (PMID 36362563, 2022).
diphtheria (1 paper, 2008). A Gram-positive bacterial infection caused by Corynebacterium diphtheriae. "Anti-mouse CD40 mAb or isotype control mAb were co-entrapped individually in cationic liposomal vehicles with pneumococcal polysaccharides or diphtheria and tetanus toxoids." (PMID 18523585, 2008). "As the two major toxoids in use, diphtheria (DT) and tetanus toxoids (TT), are co-administered, usually along with a third, pertussis component, we incorporated DT and TT into liposomes along with CD40 antibody or its isotype control." (PMID 18523585, 2008).
Disseminated intravascular coagulation (1 paper, 2021). Disseminated intravascular coagulation is characterized by the widespread activation of coagulation, which results in the intravascular formation of fibrin and ultimately thrombotic occlusion of small and midsize vessels. "We have previously demonstrated that CD40 ligation on liver macrophages initiates a pathophysiological cascade of endothelial cell activation, disseminated intravascular coagulation (DIC), vaso-occlusion, resulting in liver ischemia." (PMID 33763072, 2021).
disseminated tuberculosis (1 paper, 2022). "We present a case of active disseminated tuberculosis in a kidney transplant recipient treated with an anti-CD40 monoclonal antibody, who had been previously exposed to an active form of the disease, but latent tuberculosis (LTBI) was repeatedly ruled out prior to transplantation." (PMID 35986231, 2022).
dysplasia (1 paper, 2020). A usually neoplastic transformation of the cell, associated with altered architectural tissue patterns. "When comparing other groups, CD40, TIM-3, and CD27 also significantly discriminated ICC group from dysplasia and Ctrl HPV+ groups (AUC ranging from 0.82 to 0.91)." (PMID 32802959, 2020).
edema (1 paper, 2020). An abnormal accumulation of fluid beneath the skin, or in one or more cavities of the body. "CD40 transcription was not altered by exposure to hydrostatic pulmonary edema fluid; however, exposure to ARDS pulmonary edema fluid resulted in a 5-fold increase of CD40 mRNA levels in hMSCs (p-value 0.04)." (PMID 33021986, 2020).
emphysema (1 paper, 2019). "In vivo, erythromycin decreased NETs in the airway and ameliorated emphysema with Th1 and Th17 cell down-regulation and CD40+ and CD86+ mDCs suppression in mice chronically exposed to cigarette smoke." (PMID 31515489, 2019). "Moreover, Th1 and Th17 cells, and CD40 and CD86 in the lungs of mice with emphysema positively correlated with the levels of extracellular DNA in BALF (r = 0.758, P = 0.011; r = 0.830, P = 0.003; r = 0.855, P = 0.002; r = 0.673, P = 0.033; respectively)." (PMID 31515489, 2019).
endotoxemia (1 paper, 2016). "TLR4-mediated and CD40-mediated signals received by macrophages during early endotoxemia are known to promote IL-10 transcription, which can in turn signal to degrade mRNA encoding TNFα, thus identifying IL-10 as a crucial feedback control molecule that mediates cessation of inflammation." (PMID 27125280, 2016).
Erythema (1 paper, 2010). Redness of the skin, caused by hyperemia of the capillaries in the lower layers of the skin. "The disease onset occurred around Day 28 in control siRNA treated group, versus Day 35 in CD40 siRNA treated group, as judged by erythema and swelling of joints." (PMID 20102615, 2010).
erythema multiforme (1 paper, 2021). Erythema multiforme (EM) refers to a group ofhypersensitivity disorders characterized by symmetric red, patchy lesions, primarily on the arms and legs. "In order to study the role of CD40 in human diseases, the cellular infiltrates of the skin of eight patients with erythema multiforme and six with SJS/TEN had been analyzed." (PMID 33717075, 2021). "While CD40+ cells were similarly represented in erythema multiforme and SJS/TEN, CD40L+CD4+ T cells which may bind to CD40 on APCs were strongly represented in the perivascular and subjunctional dermis of SJS/TEN specimens." (PMID 33717075, 2021).
food allergy (1 paper, 2025). Gastrointestinal disturbances, skin eruptions, or shock due to allergic reactions to allergens in food. "We have generated foundational data that could lead to additional therapies for food allergy in patients with AD by targeting S. aureus skin colonization, CD40, IL-33, basophils, and IL-4 signaling." (PMID 41005294, 2025).